XBP1 (X-box binding protein 1)
Diseases named in the same sentence as XBP1 in open-access papers (continued):
Sharing a sentence is not in itself a finding about the gene and the disease.
cancer (continued). "Through multiply molecular mechanisms, XBP1 plays a role in regulating the biology of cancer cells, such as proliferation, invasion, migration, apoptosis, and drug resistance." (PMID 32793479, 2020). "When blotted with anti-XBP-1 specific antibody, we found that all tested cancer cells expressed an active form of XBP-1s, even in the absence of BFA, Thps, and TM treatment." (PMID 31020572, 2019). "Transcriptional regulatory mechanism of XBP1 in cancer development has been well known, however, regulation of ubiquitination and degradation of XBP1 has not been elucidated yet." (PMID 30783083, 2019). "Our previous study has also demonstrated that Pin1 regulates XBP1 that has a critical role in cancer signaling." (PMID 30783083, 2019). "Here, the authors show that the glycosidase II beta subunit, PRKSCH, protects cancer cells from ER stress, by interacting with IRE1α and activating the IRE1α-XBP1 branch of the UPR." (PMID 31320625, 2019). "In cancer, activation of X-box binding protein (XBP1) has a critical role in tumorigenesis and cancer progression." (PMID 30783083, 2019). "The inositol-requiring kinase enzyme 1 alpha (IRE1α) signal also promotes cell growth in certain cancer cell types due to up-regulation of cyclin A1 via X-box binding protein 1 (XBP-1) downstream of IRE1α." (PMID 30845711, 2019). "Regulation of transcriptional activation of XBP1 plays a critical role in cancer progression and development." (PMID 30783083, 2019). "Strikingly, STF-080310, a novel IRE1α/XBP1 inhibitor, can sensitize resistant MCF7 cancer cells to tamoxifen through specifically disrupting the splicing of XBP1 and reducing the expression level of XBP1s." (PMID 31065692, 2019). "Different studies indicated that the IRE1α-XBP1 signaling was observed in different human cancers including breast and hepatocellular cancer." (PMID 30813301, 2019). "Both XBP1 and its spliced form have been reported to be upregulated in several cancers, and the inhibition of IRE1/XBP1 pathway has been explored therapeutically." (PMID 29311669, 2018). "Several cancer types overexpress XBP1 and CHOP factors, related to higher cell proliferation and poor patients’ prognosis." (PMID 29415493, 2018). "The involvement of the IRE1α-XBP1 signaling in cancer progression has been the subject of many studies." (PMID 30081573, 2018). "In Chinese and Korean datasets (GSE54129 and GSE24375), the positive regulation of GATA6 by XBP1 was increased from normal to cancer, while it was decreased in American dataset (TCGA-STAD) during carcinogenesis." (PMID 29745833, 2018). "Silencing XBP-1 in intratumoral suppressive DCs enhances T cell responses to cancer antigens, a result that is distinct from our observations in GVHD." (PMID 30574153, 2018). "Based on the findings of other studies investigating the effect of IRE1α-XBP1 inhibitors on other cancer types and our own results, we employed toyocamycin in subsequent assays." (PMID 29581854, 2018). "Seminal studies have determined the cancer cell-intrinsic protumoral role of the IRE1α- XBP1 and the PERK-eIF2α pathways in vivo." (PMID 28105371, 2017). "Spliced XBP1 is a crucial factor for stimulating cancer progression by promoting tumor cell survival and metastatic potential and driving dendritic cell dysfunction to further inhibit anti-cancer immunity." (PMID 27638465, 2017). "UPR activation as a cytoprotective response is supported by the fact that XBP1 overexpression in cancer cells directly promotes tumorigenesis, such as in chronic lymphocytic leukemia." (PMID 27303918, 2016). "In summary, our study provides a molecular mechanism and preclinical rationale for using doxorubicin against MM, as well as other types of cancers in which IRE1α-XBP1 signaling plays a prominent role in their pathogenesis." (PMID 27634301, 2016).
cancer (continued). "XBP1 and its spliced form XBP1s have been reported to be upregulated in several types of cancers, and blockage of the IRE1/XBP1 pathway is considered as a promising therapeutic option." (PMID 26934650, 2016). "It has been reported that XBP1 can form a complex with HIF-1 in regulating gene transcription in cancer cells." (PMID 27338006, 2016). "Treatment of U251MG cells with 4-PBA, a chemical chaperone, decreased the spliced forms of Xbp1 in basal levels and alleviated ER stress, indicating that the cancer cells we checked were under ER stress conditions." (PMID 25955804, 2015). "Increasing evidence indicates that XBP1 has critical roles in the tumorigenesis and progression of various cancer cells." (PMID 26633383, 2015). "These pathophysiological conditions trigger UPR and induce the activation of XBP-1, which helps cancer cells to survive under such harsh cytotoxic microenvironments." (PMID 25426559, 2015). "Increasing evidence demonstrates that dysregulation of XBP1 function contributes to tumorigenesis in some cancers." (PMID 26633383, 2015). "Previous studies reported that XBP1 was activated in various human cancers, including both mesenchymal and epithelial cancers." (PMID 26633383, 2015). "On the contrary, some cancer cells have constitutive activation of IRE1α–XBP1 thus inhibiting apoptosis." (PMID 26491226, 2015). "We detected upregulation of the spliced forms of Xbp1, a marker of ER stress, confirming that ER stress occurred in the examined cancer cell lines." (PMID 25955804, 2015). "Several reports suggested that the inhibition of the IRE1α/XBP1 pathway is a new anti-cancer target." (PMID 26627053, 2015). "Consistently, AR and UPR gene expression were correlated in human PCa, and spliced XBP-1 expression was significantly upregulated in cancer compared with normal prostate." (PMID 25864123, 2015). "Overall, many studies bring together evidences pointing out that XBP-1 is of particular interest regarding its potential as an anti-cancer therapeutic target." (PMID 25216759, 2014). "XBP-1 is expressed ubiquitously and is increased in many types of cancers as is the case for several downstream targets of UPR." (PMID 25216759, 2014). "To determine if PRNP gene expression in the basal carcinoma cell lines depends on ER stress, we knocked down (KD) ATF6α and XBP1 with siRNAs in the MDA-MB-231 and HS578T cell lines." (PMID 23497519, 2013). "Together, these studies indicated that down-regulated miR-214 in HCC cancer induces the over-expression of XBP-1, which in turn accelerates tumorigenesis." (PMID 22359598, 2012). "Consistent with previous reports that cancer cells often exhibit defective ER stress signaling, we found that thapsigargin (TG) treatment enhanced IRE1α and PKAc phosphorylation and upregulated XBP1 target genes such as YBX2 and TGFβ2." (PMID 41516347, 2026). "Activation of IRE1α/XBP1 signaling in skeletal muscle during cancer cachexia." (PMID 40655023, 2025). "A549 cells, like many cancer cell types, appear to have a high capacity for XBP1 splicing." (PMID 40005508, 2025). "IRE1α/XBP1 axis regulates STAT3 signaling in skeletal muscle during cancer cachexia." (PMID 40655023, 2025). "In addition, some cancer cells rely on IRE1α independently of its enzymatic activity or XBP1 splicing." (PMID 41372991, 2025). "The regulatory activity of XBP1 in promoting cancer cell proliferation has been well‐reviewed." (PMID 40105652, 2025). "XBP1 also mediates immunosuppressive phenotypes intrinsically in cancer cells." (PMID 41301006, 2025). "In the mouse model dataset, TPCS cancer cells overexpress the luminal markers Xbp1 and Fgfr3 as well as the basal stem cell markers Itga6 and Cd44, the basal marker Egfr, and the EMT‐related marker Cldn4, suggesting that TPCS are of potential to generate multiple lineages." (PMID 38582099, 2024).
cancer (continued). "Furthermore, some cetumximab-treated cancer cells that are resistant to immunogenic cell death, display increased XBP1s expression, and inhibition of XBP1 splicing restored tumor immunogenicity." (PMID 37721642, 2023). "In fact, in Xbp1-/- and Xbp1-knockdown mice cells, cancers cannot develop." (PMID 36675080, 2023). "XBP1 was reported to exert inhibitory effects on protective T cell-mediated anti-cancer immunity." (PMID 35543228, 2022). "Interestingly, our study found that the contribution of X-box binding protein-1 (XBP-1) to cancer provided new sights for this study." (PMID 35754792, 2022). "Furthermore, XBP1 expression was negatively correlated with almost all immunological biomarkers and TILs in BC patients across human cancers." (PMID 35543228, 2022). "XBP1 is upregulated in many types of cancers and correlated with a poor prognosis." (PMID 35543228, 2022). "XBP1 mRNA expression levels were the highest in BC among human cancers." (PMID 35543228, 2022). "Notably the IRE1α/XBP1 pathway is primarily associated with upregulation of UPR gene transcription but is also implicated in metabolic disorders and cancer pathology." (PMID 35784841, 2022). "In this section, we will describe the relationship between XBP1 and hallmarks of cancer." (PMID 35269888, 2022). "Furthermore, XBP1 mRNA expression levels were obviously highest in BC among human cancers and were significantly related to a good prognosis." (PMID 35543228, 2022). "In the study, we found that XBP1 is highest in BC among human cancers." (PMID 35543228, 2022). "Moreover, we further analyzed that the clinical significance of XBP1 in multiple human cancers, the expression profiles of XBP1 were observed across 33 major types of human cancer in The Cancer Genome Atlas (TCGA) database." (PMID 35991556, 2022). "According to the previous study, XBP1 is comprehensively overexpressed in cancer cells." (PMID 34094948, 2021). "In addition, XBP1 acts as an important role in protection against oxidative stress via ROS signaling pathway in several cancers." (PMID 34094948, 2021). "XBP1 was previously identified as a candidate oncogene that is induced in various cancer types." (PMID 34418985, 2021). "Research has reported that MMPs is involved in XBP1-regulated cancer progress in kinds of cancers." (PMID 34094948, 2021). "Moreover, in another in vitro model of Ras-driven cancer, XBP1 was found to promote survival, whereas RIDD was found to suppress either survival or transformation of keratinocytes." (PMID 33842465, 2021). "However, the pro-tumoural or anti-tumoural role of XBP1 in cancer is discussed and is probably context-dependent." (PMID 32111004, 2020). "Indeed, several functional studies have shown that targeting the expression or the RNase activity of IRE1 reduces the progression of various forms of cancer mostly due to ablating the prosurvival effects of XBP1 on tumor growth." (PMID 32576923, 2020). "Therefore, XBP-1 expression is believed to contribute to the survival of cancer cells by inducing BiP/GRP78 expression." (PMID 30845711, 2019). "Additionally, overexpression of XBP1s, a splicing isoform of XBP1, leads to estrogen-independent cell growth in ER-positive breast cancer cells and increases the resistance of cancer cells to tamoxifen." (PMID 31065692, 2019). "The IRE1/XBP1 axis has been the most extensively correlated with cancer progression and metastasis." (PMID 31064137, 2019). "IRE-1α-XBP1 signaling plays a significant role in cancer cell survival." (PMID 31121863, 2019). "It is possible that the ability of DSF to splice XBP1 might contribute to the cancer cell selectivity." (PMID 31064122, 2019). "Our findings suggest that the XBP1 and Fbw7 axis might be an attractive target to develop for cancer therapy." (PMID 30783083, 2019). "Moreover, expression of the dominant-negative form of IRE1α or inhibition of XBP1 by siRNA induces reduction in angiogenesis during tumorigenesis and in cancer growth in xenografts model." (PMID 30081573, 2018).
cancer (continued). "Furthermore, a recent study showed that IRE1α-XBP1 signaling also shapes the pro-tumoral attributes of macrophages in cancer." (PMID 28105371, 2017). "It has been suggested that some cell types, such as those involved in the development of cancer cells, may require XBP-1 for survival." (PMID 28278289, 2017). "The IRE1α-XBP1 pathway plays a critical role in various cancers." (PMID 28222747, 2017). "Recently, XBP1 was reported to bind to the promoter regions of VEGF‐A in cancer cells." (PMID 27133203, 2016). "Indeed, cancer cells are frequently reported to have an elevated level of spliced XBP1 relative to normal cells, and moreover, the conditioned expression of XBP1s promotes tumorigenesis." (PMID 26068456, 2015). "XBP1 was known to be activated under stressful conditions in various cancer cells." (PMID 26633383, 2015). "Moreover, the activated IRE1α/XBP1 pathway plays an essential role in resistance and adaptation to ER stress by many types of cancer cells." (PMID 26254280, 2015). "Moreover, XBP1 also activates the transcription of a variety of genes involved in cancer cell survival, immune cell differentiation, glucose homeostasis and lipid metabolism, and autophagic response." (PMID 26572862, 2015). "Our results suggest that XBP1 exerts its effect on OS probably by influencing PI3K/mTOR signaling, which could be a novel mechanism by which XBP1 promotes cancer progression." (PMID 26633383, 2015). "In addition, the expression levels of other genes related to ER stress, such as IRE1, ATF6, PERK and XBP1 also increased following NASTRp treatment in human cancer cells." (PMID 25897662, 2015). "Additionally, XBP1 mRNA splicing processed by IRE1 causes a reading frame shift which is translated into a spliced form of XBP1 protein, which is an active transcription factor in various cancers." (PMID 27668268, 2015). "The pathways through which IRE1α/XBP-1 branch is involved in progression of different cancers is still unknown and few hypotheses begin to emerge." (PMID 25216759, 2014). "Based on these data we suggest that the development of IRE1α kinase inhibitors could prevent RNase activity and subsequent splicing of XBP1 which would be of potential therapeutic use for the treatment of cancer." (PMID 24524643, 2014). "XBP-1 is often over-expressed in cancer cells and, importantly, increases drug resistance by interfering with cell cycle regulation and by down-regulating tumor apoptotic responses to anti-cancer drugs." (PMID 24723911, 2014). "Moving forward, considerable attention should be given to interpreting how these findings translate to our understanding of XBP1 related pathologies and the therapeutic potential of exploiting these mechanisms in certain disease states such as inflammatory disorders and cancer." (PMID 24710528, 2012). "Notably, IRE1α’s recent identification as a dynamic scaffold that coalesces with stress granules amplifies its RNAse efficiency under ER stress, accelerating XBP1 splicing and potentiating nociceptive signaling —a process conserved across neuropathic pain and cancer." (PMID 40722704, 2025). "To understand whether XBP1 has any role in regulating the lipid droplet content in skeletal muscle during cancer cachexia, we performed immunostaining for the Perilipin 2 protein, which is one of the most abundantly expressed lipid droplet-coating proteins in skeletal muscle." (PMID 40655023, 2025).
cancer (continued). "Thus, we concluded that PIE-induced malignancies may be possible link to IRE1α/XBP1-mediated M2-like TAMs polarization and PD-L1 up-expression." (PMID 38554175, 2024). "Indeed, an altered XBP1 pathway has been related with a variety of diseases, such as cardiovascular diseases, metabolic diseases, neurodegenerative diseases and cancer." (PMID 39268577, 2024). "Therefore, XBP1 might play a double-face role in the development and progression of cancers, and the molecular mechanism regulated by XBP1 is still obscure; Therefore, the different pathways that XBP1 is involved in need to be further investigated." (PMID 35543228, 2022). "Accumulating evidence suggests that the IRE1α-XBP1 pathway plays a critical role in the development of various cancers, and in particular, the levels of XBP1 isoforms may be critical in the fate determination of cancer cells, but the specific mechanism remains to be investigated." (PMID 36092910, 2022). "The cytotoxic effect of IRE1α/XBP1 inhibition by 4μ8C correlated with the downregulation of c-Myc in BL cells, given that the latter may engage a positive feedback loop with XBP1s to sustain the survival of cancers." (PMID 36012375, 2022). "In TNBC, XBP1 hyperactivation promotes an adaptive response to ER and hypoxic stress through the regulation of hypoxia-inducible factor 1α (HIF1α) leading to enhanced cancer cell survival and decreased patient survival, as well as promoting TNBC resistance to paclitaxel and doxorubicin treatments." (PMID 33842465, 2021). "Moreover, DNA damage in cancer cell line HCT116 even suppresses IRE1α-XBP1 to stabilize proapoptotic protein BCL-2 interacting killer that contributes to apoptotic cell death, suggesting that DNA damage appears not to activate canonical UPRER in proliferating cells." (PMID 33208465, 2021). "Therefore, XBP1 may be a predictive biomarker of cancer development and progression and a potential therapeutic target." (PMID 32793479, 2020). "Several studies in normal cells, cancer and disease models have previously identified chemicals that activate or block the RNAse and/or kinase activity of IRE1ɑ and modulate the Xbp1s:Xbp1u ratio as potential therapeutic modifiers of the IRE1ɑ/XBP1 signalling pathway." (PMID 31260448, 2019). "Through an in silico drug discovery approach based on protein-compound virtual docking, we identified the anthracycline antibiotic doxorubicin as an in vitro and in vivo inhibitor of XBP1 activation, a previously unknown activity for this widely utilized cancer chemotherapeutic drug." (PMID 27634301, 2016). "However, the specific regulatory mechanism of activation of the IRE1α/XBP1 pathway in cancer cells is unknown." (PMID 26254280, 2015). "Furthermore, enhanced activation of IRE1 may have a cytoprotective effect leading to cancer progression via XBP1 mRNA splicing." (PMID 26491226, 2015). "The resulting IRE1α–XBP1 dysfunction provides a potential explanation for the dysregulation of ER chaperones and UPR components commonly observed in cancers." (PMID 41516347, 2026). "Activation of the UPR can promote cancer progression by regulating cytokine secretion in TAM, with XBP1 playing a crucial role." (PMID 40547943, 2025). "Disease progression and treatment relapse are attributed to MM cancer stem cells (CSCs) and signaling molecules such as MUC1 and XBP1." (PMID 40179083, 2025). "In cancer cells, IRE1/XBP1 is a key regulator of ER stress that controls cell survival and/or apoptosis." (PMID 40976979, 2025).